RNU6-607P (RNA, U6 small nuclear 607, pseudogene)
Gene: Small nuclear RNA gene on chromosome 8 (37,668,898 to 37,669,005, forward strand). Ensembl gene ENSG00000223215.
Homologues: Orthologues: chimpanzee U6 (98% identical), macaque U6 (97% identical), guinea pig U6 (61% identical), mouse Gm24631 (52% identical). Paralogues in human: RNU6-169P (77% identical), RNU6-386P (77% identical), RNU6-1287P (76% identical), RNU6-1013P (75% identical), RNU6-1091P (75% identical), RNU6-1152P (75% identical), RNU6-797P (75% identical), RNU6-812P (75% identical), RNU6-1155P (74% identical), RNU6-1331P (74% identical), RNU6-15P (74% identical), RNU6-188P (74% identical), and 1282 more.